IL1B (interleukin 1 beta)
Diseases named in the same sentence as IL1B in open-access papers (continued):
Sharing a sentence is not in itself a finding about the gene and the disease.
infection (continued). "Activation of proinflammatory cytokines such as IL-1β is a hallmark of bacterial infections that is crucial for host-defense responses to infection and injury." (PMID 28512644, 2017). "Concomitantly, AP-3-deficient mice exhibit higher mortality and produce less IL-1β, IL-18, and IL-17 than controls upon oral STm infection." (PMID 29253868, 2017). "Pro-inflammatory cytokines, including IFN-γ, TNF-α, IL-6, and IL-1β, are actively produced during the immune response to fight against pathogenic infection." (PMID 28454116, 2017). "Intriguingly, infection of DCs with virulent M. tuberculosis prior to infection with M. smegmatis reduced the IL-1β release, which was associated with an impaired IFN-β response." (PMID 29230217, 2017). "As trauma is often associated with infection, infiltrating monocytes/macrophages and local IL-1β release at the site of inflammation are desirable." (PMID 28757683, 2017). "Among the various pro-inflammatory cytokines, the expression of IL-1β appeared to be highly susceptible to VvpM mutant infection." (PMID 28848713, 2017). "TNF, IL-1β and IL-6 are cytokines referred to as pyrogenic and pro-inflammatory cytokines which predominate during infection and inflammation, associated with chronic inflammatory diseases." (PMID 28642550, 2017). "The local infection caused by injection of bacteria in the muscle or notochord induced the expression of IL-1β mainly around the site of infection." (PMID 27540375, 2016). "As reported in this study, high BALF levels of IL-1β are associated with tissue damage in the early stages of the infection." (PMID 27160189, 2016). "This IL-1β production in response to infection with KIM5 ΔYopK was eliminated in NLRP3/NLRC4 deficient cells, but was independent of Pyrin." (PMID 27911947, 2016). "Others have reported the activation of NLRP3 complexes and recruitment of caspase-1, together with IL-18/IL-1β release, in primary microglia and in macrophages stimulated by infection-associated agents." (PMID 28096568, 2016). "Another frequent observation is the suppression of IL-1β and neutrophil chemoattractants—these effects are, however, associated with both beneficial and harmful consequences for the infection outcome." (PMID 28082986, 2016). "IL-1 is important for neutrophil recruitment during Ft LVS infection, but Nlrp3-deficient mice have increased neutrophil numbers despite diminished IL-1β." (PMID 27926940, 2016). "To test if the diminished production of IL-1β in infected Axl-/- mice was causal for their increased susceptibility to IAV, we administered recombinant IL-1β intranasally to WT and Axl-/- mice on days 1, 2, and 3 post-infection with 10 PFU of PR8." (PMID 27350258, 2016). "A recent study examined intranasal Ft LVS infection of IL-1-/- and IL-18-/- mice, revealing increased susceptibility of IL-18 deficient mice and a critical role for IL-1β in the early production of protective anti-Ft LPS IgM by B1a B cells." (PMID 27926940, 2016). "HGPg also caused significant upregulation in the secretion of IL-1β into medium at 6 and 12 h after infection in HGFs." (PMID 28083517, 2016). "IL-1β is intricately connected to the inflammasome, which is commonly found in innate cells and functions as a molecular platform from which pro-inflammatory cytokines (such as IL-1β) can mature following activation caused by cellular- stresses and infection." (PMID 27050308, 2016). "Investigations on single nucleotide polymorphisms revealed an increased infection risk for IL-1β (-31), CX3CR1 (Thr280Met), IL-10 (-1082) as well as IL-1β (-511)." (PMID 28025605, 2016). "In a GBS-infection model, IL-1β deficiency has been associated with selective impairment in the production of the neutrophil chemokine CXCL1." (PMID 27527222, 2016). "Two IL1B SNPs were associated with a decreased risk of infection: rs16944 AG (OR = 0.52, 95% CI: 0.28–0.97) and rs3136558 TC (OR = 0.50, 95% CI: 0.29–0.88)." (PMID 26657940, 2015).
infection (continued). "Here, Cl-CATH2 prominently blocked the genes of LPS–induced key pro-inflammatory cytokines (TNF-α, IL-6, and IL-1β) and iNOS, which can produce NO in a variety of tissues, and detectable in many cell types associated with infection and inflammation." (PMID 26194630, 2015). "IL-1R1−/− mice, deficient for cell signaling in response to both IL-1α and IL-1β, are more susceptible to most infections, including those caused by GAS, GBS, and SPN." (PMID 26500655, 2015). "TNF, IL-1β and IL-6 pro-inflammatory cytokines play crucial roles in inflammation, infection, and responses to stress caused by different types of infections." (PMID 26657940, 2015). "Like BMDMs, BMDCs derived from ASC-, AIM2-, or caspase-1-deficient mice are defective for cell death, IL-1β secretion and caspase-1 processing in response to infection with wildtype F. novicida." (PMID 25879288, 2015). "This review summarizes the role of IL-1β during infections caused by streptococcal pathogens, with emphasis on emergent mechanisms and concepts countering paradigms determined for other organisms." (PMID 26500655, 2015). "Strikingly, in both strains of mice there was also a significant increase in the number of ILC3s within the mLN after infection, likely reflecting IL-1β production and/or intestinal damage caused by the parasite." (PMID 25575242, 2015). "On univariate analysis for the BAL data, % neutrophils, IL-1β, IL-6, IL-8, IP-10, NTHi infection and respiratory viruses were inversely associated with NTHi-specific IFN-γ production by blood mononuclear cells." (PMID 26066058, 2015). "Our results demonstrate that the potential benefit of long-term use of a neutralizing antibody to IL-1β in humans at high risk for atherosclerotic vascular disease must be substantial enough to counter the increased risk of infection." (PMID 25010102, 2014). "Our data show that primary infection induces significantly higher amounts of IFNγ in IL-1β and IL-1R deficient mice than in wild-type mice on day 14 post-inoculation." (PMID 25198773, 2014). "For infection, in this sterile model, the presence of rPVL was associated with an increase in the levels of IL-1β and IL-8 in the BALF, and IL-8 in lung lysates." (PMID 24905099, 2014). "The enhanced production of IL-1β compared to WT after infection was associated with increased epithelial damage, cell infiltration and CFU." (PMID 25500839, 2014). "IL-1β is related to some of cytokines, which cause a variety of biological effects associated with infection, inflammation, and autoimmune processes." (PMID 25396430, 2014). "Recent data from a mouse model of S. aureus, however, clearly reveals an important immuno-modulatory role for IL-19 and IL-24 in suppressing IL-1β and IL-17 dependent effector pathways and promoting susceptibility to infection." (PMID 24699268, 2014). "On the contrary, IL-1β by itself has been directly linked to autoimmune disorders and also to immunopathogenesis after infection with all kinds of pathogens including viruses." (PMID 24460592, 2014). "Mounting evidence indicates that the infection-induced production of pro-inflammatory/Th1-cell-polarizing cytokines, including interleukin-1β (IL-1β) and tumor-necrosis factor (TNF), is associated with premature labor and pre-term delivery." (PMID 25139335, 2014). "To demonstrate that reduced IL-1β at the site of infection in peptide 2/4-VLP vaccinated mice was associated with decreased agr-mediated virulence factor expression, we measured Hla in tissue homogenate by Western blot analysis." (PMID 25379726, 2014). "Infection of caspase-1 deficient BMDMs with live B. pertussis induced release of IL-1β into the culture supernatant, although at significantly lower levels than wild-type cells." (PMID 25198773, 2014). "Contrary to what we saw for DUSP-1, challenge with L. pneumophila Dot+ led to a significant increase in cell-associated pro-IL-1β levels after 4 hrs of infection." (PMID 25058342, 2014).
infection (continued). "Infection with the PVL+ strain was associated with greater IL-1β release in the BALF than was the case with a ΔPVL mutant strain." (PMID 24905099, 2014). "Association of circulating IL-1β levels and high susceptibility to endotoxic shock in mice primed by infection with P.chabaudi." (PMID 24453977, 2014). "In these experiments, LPS-primed BMDM from WT and Pkcδ-deficient mice were infected with WT or S325 (T3SS-deficient mutant) Shigella, and IL-1β release was evaluated at different time points and bacterial/macrophage ratios after infection." (PMID 24516390, 2014). "Though not statistically significant at all time-points sampled, transcripts encoding the pro-inflammatory cytokines IL-1β and CXCLi2 were up-regulated in the lung during the early phase of infection." (PMID 24524463, 2014). "After both 4 and 8 hours of infection, many of the up-regulated genes were those that encode pro-inflammatory cytokines (IL-1α, IL-1β, IL-6 and TNF-α) and chemokines (CCR7 and IL-8), all of which have been implicated in RA and CVD pathogenesis." (PMID 24874661, 2014). "For the i.n. infection, cytokine levels were very low locally at 1.5 hours but increased levels of IL-6, KC and IL-1β were found at 3 hours for susceptible mice (S/C-KO)." (PMID 24498223, 2014). "Increased transcript levels of TNFA, as well as IL-1B, have also been associated with active disease/infection." (PMID 23457650, 2013). "Infection activates the maternal immune system, which causes production of the proinflammatory cytokines IL-1β and TNF-α." (PMID 23840918, 2013). "IL-1α levels were slightly increased in IL-1β deficient mice, and conversely, IL-1β levels were slightly increased in IL-1α deficient mice during the first 2 months of infection." (PMID 25400917, 2013). "In previous reports, deficiency in IL-1α or IL-1β led to either early death after M. tuberculosis infection or survival up to 3–6 months at lower dose infection." (PMID 25400917, 2013). "Yet in vivo with a live infection, IL-1β levels in the lung are unaffected by loss of ASC or caspase-1 and bacterial burden and mortality in inflammasome-deficient mice are not significantly different from WT mice." (PMID 24409181, 2013). "IL-1 receptor (IL-1R) and IL-1β knock-out mice are more susceptible to M. tuberculosis infection, exhibiting high bacterial burden in the lungs and increased mortality early in infection." (PMID 23849220, 2013). "Down-regulation by 2–4 fold of genes encoding immune mediators such as IFN-γ, IL-1B, IL-1m, lactoferrin (Ltf) and nitrous oxide synthase 2 (Nos2) was consistently observed at 5 and 9 days post-infection." (PMID 23861742, 2013). "Studies in caspase-1 knock-out mice have shown that these animals have an increased susceptibility to a variety of infections, because IL-1β maturation is impaired." (PMID 23935506, 2013). "Mice deficient only for IL-1α or IL-1β had less pronounced pulmonary inflammation on day 35 post-infection." (PMID 25400917, 2013). "Deficiency in either IL-1α or IL-1β allowed some bacterial growth restriction on day 35 post-infection, and there was a limited increase in bacterial load at 2–3 months post-infection." (PMID 25400917, 2013). "The levels of IL-17A were also reduced in mice deficient for both IL-1α and/or IL-1β or IL-1R1 at 5 weeks post-infection and in IL-1α or IL-1β single deficient mice at 8 weeks post-infection." (PMID 25400917, 2013). "Abundance of inflammatory cytokines (TNF-α, IL-1β and IL-17) in CL supports the extensive inflammatiory nature of the disease which causes tissue damage at the site of infection." (PMID 24267152, 2013). "Macrophages and PMN are major sources of IL-1β, a cytokine that has been implicated in both pathology and clearance of infection." (PMID 24073293, 2013). "IL-1β is responsible for recruiting immune cells to the site of infection, and high concentrations of IL-1β have been reported to predispose to acute lung injury." (PMID 23478252, 2013).
infection (continued). "Caspase-1 activation and the processing/release of IL-1β were completely inhibited in the infection of NLRP3- and ASC-deficient BMMs, whereas inhibition was marginal in NLRC4-deficient cells." (PMID 23357873, 2013). "Compared to MLV-infected cells, VR-2385 infection caused significantly higher level of expression of proinflammatory cytokines, including interleukin 1 beta (IL-1beta) and IL-8." (PMID 23637938, 2013). "IL-1α and IL-1β double deficient mice exhibited strongly increased lung weights, an indicator of lung inflammation, 5 weeks post-infection, as did IL-1R1 deficient mice and TNF KO mice which succumbed at 4 weeks." (PMID 25400917, 2013). "We have recently reported that the intracellular infection of macrophages with B. cenocepacia K56-2 is associated with caspase-1-dependent release of IL-1β." (PMID 22848580, 2012). "It should also be noted that since IL-1β- and IL-1R-deficient mice ultimately clear these infections, compensatory mechanisms exist that eventually promote bacterial clearance." (PMID 23209417, 2012). "The improved survival in the P2X7R deficient mice correlated with diminished levels of IL-1β and IL-6 and reduced neutrophil infiltration in the early phase of infection." (PMID 22558229, 2012). "Taken together, IL-1β and neutrophil abscess formation during an infection are functionally, temporally and spatially linked as a consequence of direct IL-1β production by neutrophils." (PMID 23209417, 2012). "IL-1β mediates a variety of host acute responses to infection, including fever, loss of appetite and somnolence." (PMID 22546005, 2012). "Infections of macrophages with ΔT2SS, ΔT3SS, ΔT4SS-1, and ΔT6SS mutants were associated with reduced IL-1β secretion." (PMID 22848580, 2012). "During infection with pathogenic bacteria, assembly and activation of the inflammasome result in caspase-1 activation and IL-1β secretion, which are critical for an effective immune response." (PMID 22558425, 2012). "While the TNFα transcript was not clearly up-regulated, either in resistant or in susceptible fish, the key pro-inflammatory cytokine IL1β was strongly induced by the infection." (PMID 22720048, 2012). "Among the other tested pro-inflammatory cytokines including TNFα1, TNFα2 and IFNγ, none appeared consistently induced by the infection either in micro-arrays or in QPCR, underlining the primary implication of IL1β in pronephros at this stage of the infection." (PMID 22720048, 2012). "The inflammasome was proposed to play an important role in host defense against Mtb since mice deficient in IL-1receptor (IL-1RI), IL-1β or IL-18 are more susceptible to infection with Mtb." (PMID 22911706, 2012). "Cell death was measured by lactate dehydrogenase (LDH) release assay and secreted IL-1β was measured by enzyme-linked immunosorbent assay (ELISA) at 24 hr post infection." (PMID 22563435, 2012). "This “low MOI" infection procedure has previously been shown to cause cytotoxicity, activation of caspase-1, and high level secretion of IL-1β in macrophages." (PMID 22563435, 2012). "Il1b haplotype was associated with variation in the probability of infestation by ticks and fleas and infection with Bartonella." (PMID 22039363, 2011). "The loss of plasma membrane integrity observed during H37Rv-infection together with DNA fragmentation and IL-1β release is consistent with pyroptosis or pyronecrosis." (PMID 21637850, 2011). "Expression of IL-1β is critical for host immunity to M.tuberculosis, since mice that lack IL-1β are highly susceptible to infection and succumb in the first 40 days following infection." (PMID 21249199, 2011). "Remarkably, despite the abundance of IL-1β and IL-18, Nlrc4-/- mice were dramatically more susceptible to melioidosis than WT mice, rapidly succumbed to the infection, and had very high organ's bacteria burden and worst neutrophilic lung inflammation." (PMID 22241982, 2011).
infection (continued). "Changes in levels of transcripts encoding CCL3 (MIP1-α), CXCL8 (swine IL-8), and IL-1β were found to be very close to that indicated by SAGE with all declining as the infection progressed." (PMID 22331987, 2010). "Tissue distribution results showed that GSDME and IL-1β transcription in the bursa of Fabricius and kidneys were significantly upregulated by more than five-fold (p < 0.01) following vvIBDV infection, indicating a close association with vvIBDV-induced tissue lesions." (PMID 42076745, 2026). "N. caninum infection induces the release of IL-1β and IL-18, cleaved caspase-1, and cell death in mouse bone marrow-derived macrophages, while infection of mice deficient in NLRP3, ASC, and caspase-1/11 leads to a decrease in IL-18 production and an increase in IFN-γ in the serum." (PMID 41357231, 2025). "In addition to cell death, LF82 infection resulted in secretion of proinflammatory cytokines IL-1β, IL-6, IL-8, and TNF-α, indicating a causative or at least exacerbating role of AIEC in CD." (PMID 41163391, 2025). "In addition, the expression of the il1b and isg15 transcripts also increased in Samhd1-deficient larvae following infection." (PMID 40352920, 2025). "IL-1β is essential for immune protection against TB in the early stage of infection, while prolonged production is associated with neutrophil infiltration, and high IL-1β-expressing genotype is correlated with disease progression and poor treatment outcomes of TB patients." (PMID 39898042, 2025). "For example, we previously reported that P. multocida [an opportunistic pathogenic bacterium capable of causing infections in poultry, livestock, and even humans] induces macrophage-mediated inflammatory responses (e.g., caspase-1 activation and IL-1β secretion) in mice." (PMID 40267013, 2025). "Neutrophil release of IL-1β was implicated in RIPK1-dependent ETI in a mouse infection model." (PMID 39883598, 2025). "This property of T. pyogenes may cause a rapid accumulation of IL-1β in host’s tissues, thereby worsening the infection by inducing excessive inflammation." (PMID 40568580, 2025). "One study using the B.1.351 infection model linked the decrease in neurogenesis to neuroinflammation by showing that IL-1β produced by activated microglia in the hippocampus inhibited neural stem cell differentiation into mature neurons at 7 days post-infection." (PMID 39861887, 2025). "Additionally, polymorphisms in cytokine genes such as IL-1B-31C/T, IL-1B-511C/T, and IL-8-251 T/A affect both the risk of infection and the severity of associated diseases, including gastric inflammation and carcinogenesis." (PMID 40893911, 2025). "Infection with P. berghei caused liver tissue inflammation, which was shown by a significant increase (p < 0.05) in the levels of the pro-inflammatory cytokines IL-10 and IL-1β." (PMID 39726977, 2024). "In WT animals, P21 infection caused an exacerbated inflammatory response characterized by high viral loads, weight loss, lung pathology and a significant increase in pro-inflammatory cytokines in the lungs, including IL-1β and IL-18." (PMID 38286985, 2024). "In contrast, the injection of the viral suspension triggers a more potent proinflammatory response characterized by a significant induction of both il1b and tnfa, associated with the activation of interferon signaling as shown by the upregulation of isg15 expression at late stages of infection." (PMID 39102417, 2024). "Infection with the highly pathogenic FAdV-4 has been shown to induce inflammatory damage in many tissues, accompanied by high secretion levels of the proinflammatory cytokine IL-1β." (PMID 39597653, 2024). "Importantly, NLRP3 inflammasome is upregulated during a NTHi infection in respiratory cells and tissues and associated with caspase-1-dependent IL-1β release." (PMID 38406294, 2024).